IRS1 (insulin receptor substrate 1)
Diseases named in the same sentence as IRS1 in open-access papers (continued):
Sharing a sentence is not in itself a finding about the gene and the disease.
hepatoma (continued). "Additionally, another reports demonstrated that PYCR1 interference inhibited cell proliferation and enhanced cell apoptosis in hepatocellular carcinoma by repressing JNK/IRS1 pathway." (PMID 33062641, 2020). "Likewise, in HCV-NS5A-expressing hepatoma cells, increased phosphorylation of IRS-1 at Ser307 was shown to be involved in enhanced gluconeogenic and lipogenic gene expression, thereby hampering metabolic activity and contributing to IR." (PMID 25645159, 2015). "Accumulated IRS2 may compensate for the loss of IRS1 and enhance hepatoma cell migration by modulating cell migration-promoting effectors that are shared or not shared by IRS1." (PMID 23112878, 2012). "In fact, it has been shown that hepatoma cells overexpress IGF-1 and insulin receptor substrate-1, suggesting their importance in HCC development." (PMID 36831004, 2023). "Overnight incubation of hepatocellular carcinoma (HCC) cells (i.e., FOCUS) with alcohol blunts the insulin-induced increase in the phosphorylation of the insulin receptor-β subunit, IRS-1 and AKT." (PMID 26426068, 2015). "Here, we report that AFB1 stimulates IGF-IR phosphorylation, down-regulates IRS1, but up-regulates IRS2 expression, which contributes to AFB1-induced hepatoma cell migration." (PMID 23112878, 2012). "E-box elements in the IRS-1 promoter and proteins that bind to these elements positively regulate IRS-1 expression in HepG2 hepatocellular carcinoma cells." (PMID 19534786, 2009). "In HFD-induced IR mice livers and palmitate (PA) -induced HepG2 cells (human hepatocellular carcinoma cell line), LBP enhanced the phosphorylation of insulin receptor substrate-1 (IRS-1), phosphatidylinositol 3-kinase (PI3K), and protein kinase B (AKT), thus promoting insulin signaling transduction." (PMID 41601904, 2026). "Another group observed that PYCR1 gene silencing could inhibit the proliferation of hepatoma cells, promote apoptosis, and significantly inhibit the volume and size of transplanted tumors in nude mice by regulating the JNK/IRS1 pathway." (PMID 35293266, 2022). "Notably, we found that miR-27b levels in human hepatoma cell, Huh7, influence the expression of numerous components of the insulin signaling pathways including the INSR and insulin receptor substrate 1 (IRS1)." (PMID 33212990, 2020). "In hepatoma cells expressing GHSR1a, ghrelin stimulates the MAPK signaling pathway characterized by Tyr phosphorylation of insulin receptor substrate-1 (IRS-1) and binding of growth factor receptor-bound protein 2 (GRB2) to IRS-1, an upstream signaling molecule of MAPK." (PMID 24651458, 2014). "Since AFB1 induces IGF-IR phosphorylation, up-regulates IRS2, but down-regulates IRS1, it is unclear how AFB1 may affect hepatoma cell proliferation." (PMID 23112878, 2012). "Other pathways shown to be altered by PYCR1 interference are the p38 MAPK pathway in NSCLC and the IRS1/JNK pathway in hepatocellular cancer, although we could not confirm this in MM (data not shown)." (PMID 35105345, 2022). "Furthermore, the HCV core protein of genotype 3a promotes IRS1 (but not IRS2) degradation by upregulating SOCS7 in a human hepatoma cell line (Huh-7)." (PMID 33849568, 2021). "On the other hand, in multiple myelomas, hepatocellular carcinoma, thyroid carcinoma and osteosarcomas, increased deptor expression suppresses mTORC1 activity, which increases the phosphorylation of Akt by relieving the negative feed-back loop on PI 3 kinase/IRS-1." (PMID 30444896, 2018). "Firstly, human hepatoma HepG2 cells were exposed to varying concentrations of unsaturated (oleate) fatty acid for 18 h, but oleate did not affect the expression of INSR, IRS-1, and Akt2." (PMID 28036389, 2016). "Treatment with MG132 significantly increased IRS2 levels but not IRS1 levels in HepG2 and SMMC-7721 cells treated without AFB1, indicating that IRS2 might undergo proteasomal degradation in AFB1-untreated hepatoma cells." (PMID 23112878, 2012).
metabolic syndrome (42 papers, 2011 to 2025). A cluster of metabolic risk factors for CARDIOVASCULAR DISEASES and TYPE 2 DIABETES MELLITUS. "It has been previously reported that some of IRS-1 gene variants increases the risk of metabolic syndrome." (PMID 30305144, 2018). "Previous study found that metabolic syndrome is related with IRS-1 gene polymorphism Gly972Arg." (PMID 30305144, 2018). "Supplementation with tangeretin (43.04 ± 5.98% of control), (44.30 ± 5.09% of control), and metformin (41.80 ± 3.48% of control), (52.53 ± 12.66% of control) recovered IRS-1 and Akt protein expression compared to untreated metabolic syndrome rats (p < 0.05)." (PMID 40141836, 2025). "IRS-1 (24.33 ± 1.76% of control) and Akt (6.07 ± 1.46% of control) protein expression in liver tissue were downregulated in metabolic syndrome rats compared to normal rats (100 ± 0.00% of control), (100 ± 0.00% of control) (p < 0.05)." (PMID 40141836, 2025). "Previous studies have shown that COBLL1 and IRS1 gene polymorphisms are associated with T2DM risk and the development of metabolic syndrome." (PMID 36009479, 2022). "CCL4 inhibition mice also had decreased levels of phosphorylated IRS-1 in both skeletal muscle and liver tissues compared to those in the untreated metabolic syndrome mice, implying the beneficial effects of CCL4 inhibition on insulin signaling." (PMID 33968046, 2021). "Pin1 associates with and controls key molecules (IRS-1, CRTC2, AMPK, eNOS, Runx2 and others) involved in metabolic functions or the development of metabolic syndromes." (PMID 27618008, 2016). "JNK has also been demonstrated to act by phosphorylation of IRS‐1 at Ser636, a site that was robustly hyperphosphorylated in our metabolic syndrome subjects' muscle." (PMID 25472611, 2014). "The studies reported here evaluated the phosphorylation status by immunoblots of muscle IRS‐1 at key serines in untrained metabolic syndrome subjects and quantified those again post training." (PMID 25472611, 2014). "We evaluated the phosphorylation status of muscle IRS‐1 in 33 subjects with the metabolic syndrome and seventeen lean controls." (PMID 25472611, 2014). "Metabolic syndrome, with or without AD, has been associated with impaired brain insulin signaling, including disruptions in IRS-1 and AKT pathways, indicative of a brain insulin-resistant state." (PMID 40964391, 2025). "Accumulating evidence revealed that the inactivation of Akt and the activation of Foxo1 via inhibiting insulin receptor substrate 1 (IRS1) and insulin receptor substrate 2 (IRS2) might act as the underlying mechanism of metabolic syndromes." (PMID 34805099, 2021). "Our data showed only a small decrease in muscle IRS‐1 baseline Tyr896 phosphorylation in metabolic syndrome subjects suggesting, at least in the fasted situation, tyrosine phosphorylation was adequate (albeit with a more than two‐fold higher insulin concentration)." (PMID 25472611, 2014). "The baseline hyperphosphorylation of IRS‐1 at Ser337 and Ser636 coincides with the diminished glucose uptake into the muscle in response to increments in blood insulin concentrations in many of the metabolic syndrome subjects." (PMID 25472611, 2014). "In the present study, we speculate that the primary pathway through which GS supplementation improves dyslipidemia in hyperglycemic rats is mainly through enhanced hepatic signaling of insulin depicted by the increased transcriptional activity of Irs1 and Irs2 genes." (PMID 37110174, 2023). "In this study, we revealed for the first time that direct inhibition of CCL4 could reverse the impaired insulin signaling pathway by decreasing the phosphorylation of IRS-1 in skeletal muscle and liver tissues in mice with both type 2 DM and metabolic syndrome." (PMID 33968046, 2021). "Downregulation of hepatic insulin receptor substrate-1 (IRS-1) and protein kinase B (Akt) protein expression in metabolic syndrome rats was recovered by tangeretin (p < 0.05)." (PMID 40141836, 2025).
metabolic syndrome (continued). "The Random Forest machine learning algorithm revealed that IRS-1, p-AKT, SIRT1, and NFκB are critical predictors of metabolic syndrome severity." (PMID 40166461, 2025). "Preclinical studies have shown that in NAFLD models, FXR activation upregulates SREBP1c, IRS-1, and TNF-α while downregulating AMPK, exacerbating metabolic stress, dyslipidemia, and inflammatory/oxidative stress via downstream target regulation." (PMID 40600138, 2025). "The central mechanism of this stress induced metabolic syndrome lies in the ability of these stressor factors and cytokines to activate JNK, which phosphorylates IRS-1 (insulin receptor substrate 1) on Ser 307, thus impairing insulin action." (PMID 24758278, 2014). "Furthermore, PDPs provided detailed insights into how the individual parameters IRS-1, SIRT1, and p-AKT exhibit strong inverse relationships with metabolic syndrome." (PMID 40166461, 2025). "This study found that total IRS‐1 expression was not decreased in metabolic syndrome subjects, nor was baseline tyrosine phosphorylation at Tyr896." (PMID 25472611, 2014). "Metabolic syndrome muscle IRS‐1 had excess phosphorylation at Ser337 and Ser636 but not at Ser307, Ser789, or Ser1101." (PMID 25472611, 2014). "Phosphorylations of IRS‐1 at Ser307 (a target of JNK and IKK) and Ser1101 (a target of PKCθ) were not increased in metabolic syndrome muscle." (PMID 25472611, 2014). "The IRS‐1 serine at position 789, a target for AMPK, was not different in metabolic syndrome subjects." (PMID 25472611, 2014).
lung carcinoma (38 papers, 2009 to 2025). "In lung cancer, tumors with low IRS-1 and high IRS-2 expression were associated with poor outcomes in adenocarcinoma and squamous cell carcinoma, indicating a potential role for IRS-2 in the aggressive behavior of non-small cell lung cancer." (PMID 36975518, 2023). "In lung cancer cells, silencing of IRS1 caused proliferation andinduced phosphorylation of AKT (Antoniades etal., 1992; Han etal., 2006; Houghtonet al., 2010)." (PMID 30807634, 2019). "In a previous study of stage I NSCLC, loss of IRS-1 expression was observed more frequently in SCC than other lung cancer types, similar to our observation that decreased IRS-1 expression is associated with poor survival outcomes in SCC but not ADC." (PMID 31393907, 2019). "Although little is known about the clinical significance of the IRS proteins in human lung cancer, IRS-1 has been implicated in signaling in EML4-ALK rearranged NSCLC." (PMID 31393907, 2019). "Recent studies have analyzed the biological impact of newly identified mutations within the IRS1 gene and suggested that these mutations may be diagnostic markers for lung cancer." (PMID 38091511, 2022). "Together with the IRS-1 expression data in human breast and lung cancer, these results reveal that loss of IRS-1 expression or function may facilitate tumor progression." (PMID 19534786, 2009). "Likewise, in RAS-induced lung cancer, neutrophil elastase (NE) has been found to directly cause tumor cell proliferation by infiltrating into endosomal compartments, degrading insulin receptor substrate-1 (IRS-1), and activating phosphoinositide 3-kinase (PI3K) signaling in tumor cells." (PMID 36514901, 2022). "Since we hypothesized that mutations at or around the YXXM motifs of IRS1 mayimpact insulin signaling and the phenotype of lung cancer, we isolated thegenomic DNA from 42 tumor and 40 normal lung tissues of NSCLC patients andsequenced the coding region of IRS1." (PMID 30807634, 2019). "Previous studies have reported that neutrophil infiltration in the liver of obese mice impairs insulin signaling through elastase-mediated degradation of IRS1, a phenomenon also observed in lung cancer research." (PMID 40305335, 2025). "A study conducted in human lung cancer cells revealed that PMEPA1 contributes to TGF-β-induced EMT by the downregulation of insulin receptor substrate-1 (IRS-1) and the production of reactive oxygen species (ROS)." (PMID 38173834, 2023). "INSR and IRS-1 are both overexpression in lung cancer tissues, and IRS-1 expression had a significant positive correlation with PD-L1 expression." (PMID 36245982, 2022). "IRS-1 expression was positive in 26 (57.8%) lung cancer tissues, which was significantly higher than 10 (33.3%) cases in adjacent tissues (X2 = 4.309, P < 0.05)." (PMID 36245982, 2022). "The results showed that INSR and IRS-1 are expressed in both lung cancer and adjacent normal tissues." (PMID 36245982, 2022). "Spearman rank correlation was used to analyze the correlation between INSR, IRS-1, and PD-L1 expressions in nonsmall cell lung cancer." (PMID 36245982, 2022). "The expression of INSR and IRS-1 in 45 cases of nonsmall cell lung cancer and 30 cases of adjacent normal lung tissues was detected by immunohistochemical staining." (PMID 36245982, 2022). "There was a positive correlation between the expression of IRS-1 and PD-L1 in nonsmall cell lung cancer (r = 0.373, P < 0.005)." (PMID 36245982, 2022). "Phosphorylation of IRS1S1101 increased in ZNF322A-silenced H1299 lung cancer cells which suggests ZNF322A is a regulator for IRS1/AKT/mTOR signaling pathway in NSCLC." (PMID 32576196, 2020). "On the other hand, we demonstrated that in AXL-low-expressing EGFR-mutated lung cancer cells, osimertinib exposure increased protein expression and phosphorylation of IGF-1R and thereby restored the survival signal mainly via Gab1 and IRS1 to emerge tolerant." (PMID 32929081, 2020).
lung carcinoma (continued). "To ascertain the stimulatory effect of ZNF322A on lung cancer in the IRS1/PI3K/AKT pathway, we further analyzed IRS1 and AKT expressions of ZNF322A-silenced A549 cells at 48 h post-transfection by immunoblotting." (PMID 32576196, 2020). "Neutrophil-derived elastase hydrolyses insulin receptor substrate-1 (IRS1) in the cytosol of lung cancer cells, leading to an altered regulation of phosphoinositide 3-kinase (PI3K)." (PMID 32733461, 2020). "Neutrophil elastase (NE) directly stimulates the proliferation of lung cancer growth, through the degradation of insulin receptor substrate-1 (IRS-1) and can be directly induced by hypoxia." (PMID 31461847, 2019). "The recent identification of IRS-1 mutations in NSCLC that suppress migration supports a negative regulatory role for IRS-1 in lung cancer progression." (PMID 31393907, 2019). "Previous studies also showed that PMEPA1 can regulate EMT in lung cancer cells by modulating the ROS and IRS-1 signaling pathways." (PMID 28511643, 2017). "MiR-126 has been widely reported as a tumour suppressor in lung cancer due to targeting IRS1, EGFL7, Crk, and SLC7A51318, or by means of inhibiting angiogenesis and lung metastasis during lung cancer." (PMID 29127370, 2017). "NE degrades insulin receptor substrate 1 (IRS-1) in hepatocytes, inhibiting the insulin-driven signal transduction, akin to a mechanism proposed previously in lung cancer cells." (PMID 27679792, 2016). "Therefore, it is of great significance to explore the correlation between the expression levels of INSR, IRS-1, and PD-L1 and reveal the potential mechanism of insulin pathway-related receptors in the occurrence and development of lung cancer." (PMID 36245982, 2022). "Moreover, it was previously shown that degradation of IRS-1 in lung cancer cells generated PI3K hyperactivity." (PMID 23877285, 2013). "The conclusion drawn from the lung cancer study was that downregulation of IRS-1 may be an early event in NSCLC development." (PMID 19534786, 2009). "Moreover, the insulin receptor substrate 1 (IRS1) has been shown to be crucial for the generation of DTPs, and combinations of EGFR and IRS1 inhibitors were highly effective in models of EGFR-mutated lung cancer that were examined in animals." (PMID 37894376, 2023). "Researches showed that genomic changes of IRS1 could lead to development of lung cancer." (PMID 33162799, 2020). "Our data also build on a recent report by Rai and co-workers in which delivery of miR-7 to EGFR inhibitor-resistant lung cancer cells suppressed growth in vitro and in vivo, an effect that was associated with decreased expression of EGFR as well as its downstream kinases RAF1 and IRS1." (PMID 23115635, 2012). "Neutrophils also release elastase, which degrades insulin receptor substrate-1 (IRS-1), enhancing tumor cell proliferation in a K-RAS-driven lung cancer mouse model." (PMID 39941753, 2025). "NE derived from neutrophils can degrade insulin receptor substrate 1 (IRS1), a negative regulator, leading to the activation of phosphoinositide 3-kinase (PI3K) and promoting the proliferation of lung cancer cells both in vivo and in vitro." (PMID 38760815, 2024). "On the other hand, pharmacological JNK inhibition prevented NT157-induced IRS1 and IRS2 phosphorylation in both lung cancer cells studied." (PMID 36224313, 2022). "Insulin receptor substrate 1 (IRS1) can be phosphorylated to activate AKT kinase, which promotes the development of lung cancer." (PMID 32714651, 2020). "Previous studies have showed that miRNA-7 down-regulates the expression of EGFR and key modulators of the Akt pathway including IRS-1 and IRS-2 in glioblastoma, breast, cervical and lung cancer, which led to decreased cell survival and proliferation." (PMID 32592373, 2020). "Consistently, protein-phosphoprotein-kinase interaction network analysis revealed phosphorylation of IRS1 and HSP27 were altered upon ZNF322A-silenced lung cancer cells." (PMID 32576196, 2020).
lung carcinoma (continued). "For lung cancer, we ensure that C4BPA, SESN3, and IRS1 are highly expressed in some specific groups." (PMID 33133130, 2020). "Further, more lung cancer patients with higher levels of all three molecules (GRB10, IRS1, and IGF1R) were in stage III/IV group than the stage I/II group." (PMID 29973593, 2018). "Analysis of these shortest path genes indicates that some of these genes, such as ESR1, FDXR, ABCA1, IRS1, HSP90AA1, FOXM1, and IGBP1 are related to lung cancer." (PMID 23762832, 2013). "NE could directly promote cellular proliferation by targeting IRS-1, which activates the PI3K proliferation pathway both in fibroblasts and lung cancer cells." (PMID 34681796, 2021). "Since the IRS1/PI3K/AKT signaling pathway participates in the process of glucose transport into cells, we further examined glucose uptake by a fluorescent glucose analog, 2-NBDG, to determine the effect of ZNF322A in lung cancer." (PMID 32576196, 2020). "For lung cancer, we select five essential genes, such as PYGB, C4BPA, SESN3, MMP10, IRS1." (PMID 33133130, 2020). "Correspondingly, our study shows that the shortest path of IRS1 is designated more than 100 and is significant in both NSCLC genes and SCLC genes, indicating that it may play a crucial part in lung cancer development." (PMID 23762832, 2013). "Additionally, phosphoproteomic analysis of ALK-positive lung cancer cells with or without gilteritinib treatment revealed that gilteritinib significantly decreased phosphorylation of ALK and its adapter proteins such as IRS1/2, SOS2, or SH2B1." (PMID 33627640, 2021).